ENSG00000252409
Gene: Small Cajal body-specific RNA gene on chromosome 3 (41,687,868 to 41,688,033, reverse strand). Ensembl gene ENSG00000252409.
Homologues: Paralogues in human: SCARNA21 (55% identical).